C19orf84 (chromosome 19 open reading frame 84)
Description:
Protein adapter involved in piRNA-directed transposon methylation by connecting PIWIL4-piRNA and DNA methylation machineries. The PIWIL4-piRNA pathway plays a central role during spermatogenesis by directing transposon DNA methylation and silencing, thereby preventing their mobilization, which is essential for the germline integrity.
Tractability: No criterion of Open Targets' tractability assessment is met for any kind of drug.
Gene: Protein-coding gene on chromosome 19 (51,388,289 to 51,390,591, reverse strand). Ensembl gene ENSG00000262874.
Subcellular location: Nucleus, nucleoplasm
Subcellular location (Human Protein Atlas): Vesicles
Pathways (Reactome):
Gene expression (Transcription): Regulation of endogenous retroelements by Piwi-interacting RNAs (piRNAs)
Gene Ontology:
Molecular function: protein binding
Biological process: transposable element silencing; transposable element silencing by piRNA-mediated DNA methylation
Cellular component: nucleoplasm
Genetic constraint (gnomAD): Loss-of-function variants: 1 observed, 4.25 expected, observed/expected ratio (o/e) 0.24, 90% interval 0.083 to 1.11. That is too few expected variants to judge how well the gene tolerates losing a copy. Missense variants: 224 observed, 226.87 expected, observed/expected ratio (o/e) 0.99, 90% interval 0.88 to 1.1. Synonymous variants: 123 observed, 98.98 expected, observed/expected ratio (o/e) 1.24, 90% interval 1.07 to 1.44.
Homologues: Orthologues: chimpanzee C19H19orf84 (98% identical), macaque C19orf84 (92% identical), pig C19orf84 (69% identical), rabbit C19orf84 (67% identical), dog C19orf84 (61% identical), rat C1h19orf84 (60% identical), mouse Gm38999 (59% identical).